LINC00269 (long independently transcribed non-coding RNA 269)
Synonyms: CXorf62; NCRNA00269; FLJ33610
Gene: Long non-coding RNA gene on chromosome X (69,179,553 to 69,209,924, forward strand). Ensembl gene ENSG00000215162.
Diseases named in the same sentence as LINC00269 in open-access papers:
LINC00269 is named in the same sentence as 2 diseases in open-access papers, as found by Europe PMC text mining. Sharing a sentence is not in itself a finding about the gene and the disease.
LINC00269 shares sentences with these, for which no sentence is quoted: choriocarcinoma (1 paper); serous ovarian cancer (1).